EGFR (epidermal growth factor receptor)
Diseases named in the same sentence as EGFR in open-access papers (continued):
Sharing a sentence is not in itself a finding about the gene and the disease.
lung cancer (continued). "For example, in advanced lung cancer, smoking status is linked to higher mutational burden, higher rates of C > A transversion mutations, and increased frequency of EGFR alterations, the latter having subsequent impact on selection of EGFR-directed therapies." (PMID 27213592, 2016). "After adjusting for all variables, lung cancer family history remained a significant predictor of EGFR mutations (Odds ratio 1.53, 95% CI 1.02–2.27, P = 0.035)." (PMID 27449093, 2016). "The results are also in agreement with a recent report demonstrating the significant upregulation of IL-8 in gefitinib-resistant, EGFR mutated lung cancer cells." (PMID 27248176, 2016). "EGFR mutation positive lung cancer cell lines showed enhanced ability to accumulate cisplatin in cell during hyperthermic treatment." (PMID 26654941, 2016). "This mutation causes that more than 50% of EGFR-mutated lung cancers develop acquired resistance to erlotinib or gefitinib." (PMID 27869781, 2016). "In lung adenocarcinoma patients with common sensitizing EGFR mutations, the content of mutant DNA in lung cancer tissue samples correlated with the treatment response to EGFR-TKI." (PMID 27368002, 2016). "In our current report, clinical cases have shown that EGFR kinase domain mutation positive lung cancers respond dramatically to combinational treatment of hyperthermia and cisplatin." (PMID 26654941, 2016). "Currently, an effective alternative therapy is desperately needed for lung cancer patients positive for EGFR kinase domain mutations." (PMID 26654941, 2016). "The mutation frequency of epidermal growth factor receptor (EGFR) is approximately 35%–40% among Asian patients with stage IV non–small cell lung cancer (NSCLC)." (PMID 27001083, 2016). "In lung cancer, EGFR mutations in ctDNA have been associated with prognosis and utilized for determining therapy (e.g., activating mutations that confer sensitivity to tyrosine kinase inhibitors)." (PMID 27428049, 2016). "EGFR activating mutations are known to be highly specific to lung cancer, and therefore the ctDNA harboring these mutations is also highly specific to lung cancer." (PMID 27708242, 2016). "We developed and evaluated liquid biopsy assays for detection of TKI-sensitizing and T790M mutations of EGFR by droplet digital PCR (ddPCR) in EGFR mutation–positive non–small cell lung cancer (NSCLC) patients with acquired EGFR-TKI resistance." (PMID 27542267, 2016). "Second, we demonstrated that the growth inhibitory effect of erlotinib evaluated by either the SDI or CD-DST was significantly correlated to the EGFR mutation status in the clinical study using the surgically resected lung cancer tissue specimens." (PMID 27070423, 2016). "Compared to patients with exon 21 mutations, lung cancer patients harboring EGFR exon 19 deletions have both a better response rate to EGFR TKIs (70–100% vs 20–67% respectively) and improved overall survival (26–34 mos vs 8–17 mos, respectively)." (PMID 26654942, 2016). "Taking together, investigators concluded that treatment of EGFR‐mutated lung cancer cell lines with erlotinib enriched then stem‐like cells with stem‐like cell potential through EGFR‐dependent activation of Notch3." (PMID 27770511, 2016). "The frequent EGFR mutations identified in this cohort suggest an alternative therapeutic targeting avenue where lessons learnt from the treatment of lung cancer (the cancer type with the highest frequency of EGFR mutations detected) can be applied." (PMID 27146902, 2016). "We further studied the association of migration and invasion with EGFR mutant genes in lung cancer cells." (PMID 27362942, 2016). "This is the first large-scale study on lung cancer to include detailed information pertaining to both smoking and EGFR mutation." (PMID 27191886, 2016).
lung cancer (continued). "The percentage of EGFR-activating mutations in lung cancer is about 50% in East Asian patients, but only 10% in White patients." (PMID 27801674, 2016). "Epidermal growth factor receptor (EGFR) tyrosine kinase inhibitors (TKIs) are associated with favorable response in EGFR mutant lung cancer." (PMID 26862733, 2016). "Herein, we report an unexpected finding that ZEB1 plays an opposite role in EGFR-mutated lung cancer cells by acting as a suppressor of cell growth." (PMID 27456471, 2016). "We had a greater proportion of female lung cancer patients in the younger group, but the EGFR mutation rate was lower than that of the older group." (PMID 27191886, 2016). "Stable lung cancer cell lines expressing mutant (exon 19 deletion E746-A750, and exon 21 missense mutation L858R) and wild type EGFR genes are established." (PMID 27362942, 2016). "It has been reported that secondary mutations of the c-kit and EGFR genes confer acquired resistance to imatinib in GISTs and gefitinib in lung cancer respectively." (PMID 26769852, 2016). "Another conceivable reason for the good DSS results in Asian patients is a preponderance of epidermal growth factor receptor (EGFR) mutations in Asian lung cancer patients, especially East Asian NSCLC patients, than in non-Asian patients." (PMID 27244238, 2016). "Epidermal growth factor receptor (EGFR) mutation-induced drug resistance is a difficult problem in lung cancer treatment." (PMID 27610045, 2016). "Further, some genetic abnormalities, such as a loss of phosphatase and tensin homolog in glioma or triple-negative breast cancer, and epidermal growth factor receptor mutations in lung cancer, can directly upregulate PD-L1 on cancer cells." (PMID 27117582, 2016). "The era of molecular targeted therapy in lung cancer started in 2004, when activating mutations in the epidermal growth factor receptor (EGFR) and their correlation with clinical response to EGFR tyrosine kinase inhibitors (TKIs) were discovered." (PMID 26919248, 2016). "Specifically, EGF pathway over-activation, caused by such as EGFR mutation, has been identified as a prevalent mechanism for the onset and progression of lung cancers." (PMID 26926465, 2016). "Lung cancer is a disease that presents high incidence and mortality rates, and it is primarily associated with genetic mutations that affect the EGFR, KRAS, and EML4-ALK fusion proteins." (PMID 26956044, 2016). "For 40-50% of resistant lung cancers, the acquisition of a second mutation in EGFR, for example, the substitution of threonine with methionine at amino acid 790 (T790M) in exon 20, is a well-established mechanism." (PMID 27825114, 2016). "EGFR mutations were first identified in lung cancer after clinical benefit to EGFR tyrosine kinase inhibitors was observed." (PMID 27336903, 2016). "Although the EGFR tyrosine kinase inhibitors gefitinib and erlotinib have revolutionized the treatment of lung cancers, only patients with activating mutations of the EGFR gene respond to the therapy." (PMID 26810067, 2016). "For this study, a similar calculation of background noise for the EGFR c.2369C > T change was performed in 179 FFPE lung cancer specimens with an activating KRAS mutation." (PMID 27304188, 2016). "As family history of lung cancer was associated with a significantly higher EGFR mutation rate, we further evaluated the distribution of mutation subtypes." (PMID 27449093, 2016). "It is also important to note that analysis of spatial and temporal genetic heterogeneity of EGFR mutations in lung cancer tissues is sparse." (PMID 27934896, 2016). "The mechanism about how CDH5 was regulated by mutant EGFR genes and the association of EGFR mutation with angiogenesis, migration, and invasion of lung cancer cells were further studied." (PMID 27362942, 2016). "In the unadjusted model (1:2 matching, n = 387), there was a significant relationship between lung cancer family history and EGFR mutation rate (Odds ratio 1.86, 95% CU 1.20–2.87,P = 0.005)." (PMID 27449093, 2016).
lung cancer (continued). "Expression of the TUSC2/FUS1 tumor suppressor gene in TUSC2 deficient EGFR wildtype lung cancer cells increased sensitivity to erlotinib." (PMID 27845352, 2016). "In spite of the considerable published data on the prevalence of EGFR mutations in lung cancer throughout the world, only a few papers present data on EGFR, KRAS and ALK mutations in countries from Central Europe." (PMID 27655296, 2016). "Because TKIs, such as gefitinib and erlotinib, significantly improve the clinical outcome of EGFR‐mutant lung cancers, we also analyzed cachexia risk in patients with EGFR mutation by treatment with anti‐EGFR TKIs." (PMID 27485414, 2016). "Targeting oncogenic driver EGFR using reversible or irreversible TKIs has clinically benefited for a subset of lung cancer patients with EGFR mutations." (PMID 27419630, 2016). "Separate studies have shown that EGFR-D994D plays a role in lung cancer susceptibility and that it also plays a role in sensitivity to chemotherapy." (PMID 27776352, 2016). "When patients with lung cancer carry activating EGFR mutations, their first-line of treatment can be selected with EGFR-TKI, like gefitinib." (PMID 27827952, 2016). "For instance, it was well-known that EGFR-activating mutations made patients more likely to suffer from lung cancer." (PMID 27801674, 2016). "EGFR, which is frequently overexpressed or constitutively activated upon mutation, triggers the occurrence and progression of lung cancers." (PMID 26745678, 2016). "We previously reported that a fully immunocompetent mouse model of lung cancer driven by expression of mutated EGFR demonstrates responsiveness to PD-1 blockade associated with augmentation of an anti-tumour T-cell response." (PMID 26883990, 2016). "Further studies show that expression of CDH5 is decreased after the inhibition of EGFR and downstream Akt pathways in lung cancer cells with EGFR mutation." (PMID 27362942, 2016). "Our current study findings demonstrated that smoking status, EGFR mutation, tumor burden and intra-abdominal metastasis are predictive factors for the response of these lung cancer patients to pemetrexed." (PMID 27388008, 2016). "It was feasible to test EGFR mutation in cerebrospinal fluid and the combination of erlotinib with chemotheraphy would be an appropriate choice to those lung cancer patients who had brain metastasis harboring EGFR sensitive mutation." (PMID 26805738, 2016). "21% of lung cancer patients are positive for somatic mutations in kinase domain of EGFR, although higher and lower mutational rates were reported." (PMID 26646697, 2016). "Tyrosine kinase inhibitors (TKIs) targeting epidermal growth factor receptor (EGFR) have clinically benefited to lung cancer patients harboring a subset of activating EGFR mutations." (PMID 27419630, 2016). "An increased expression of CDH5 proteins was observed in PC9 and H1975 lung cancer cells with EGFR mutations." (PMID 27362942, 2016). "There were 18 duplicated cases between the two groups; hence, a total of 1713 lung adenocarcinoma patients were indicated as “Cohort-1” to evaluate the role of lung cancer family history on EGFR mutations." (PMID 27449093, 2016). "One report demonstrated a positive correlation between EGFR mutations and BM in a Caucasian population but it was performed in patients with resected early-stage lung cancer and metastatic recurrence." (PMID 27999344, 2016). "PC-9 (EGFR mutation, in-frame deletion in exon 19) and PC-9/GR (gefitinib-acquired resistant lung cancer cells) cell lines were cultured in medium containing increasing concentrations of pterostilbene." (PMID 27276704, 2016). "Currently, clinics follow ASCO 2011 and NCCN 2013 guidelines that demand that lung cancers be genotyped to confirm EGFR mutations before administering TKIs." (PMID 26646697, 2016). "Tyrosine kinase inhibitors of EGFR, including gefitinib and erlotinib, are clinically effective drugs that treat EGFR-mutated lung cancer." (PMID 27456471, 2016).
lung cancer (continued). "Further studies involving twins with lung cancer would be useful to evaluate the effects of genetic predisposition on EGFR mutations." (PMID 27449093, 2016). "These proposed “molecular surgeries” on genomic DNA in EGFR‐mutant lung cancer directly target the cause of the disease in a personalized and, it is hoped, permanent manner." (PMID 26747090, 2016). "Of note, patients with lung cancer family history had a significantly higher EGFR mutation rate (64.9% vs. 55.1%, P = 0.045) but the EGFR mutation spectrum was similar with that of the sporadic cases (P = 0.560)." (PMID 27449093, 2016). "For example, in lung cancer smoking-independent cancers are in many respects biologically distinct, having more frequent EGFR mutations, lower mutational burden, and lower rates of the C > A transversion mutations than smoking-associated lung cancers." (PMID 27213592, 2016). "In our current work, we clearly showed that IPHC-CT was effective against lung cancers positive for EGFR kinase domain mutations." (PMID 26654941, 2016). "Several clinical studies suggested the presence of clone with T790M-resistant mutation before exposure to EGFR-TKI in EGFR-mutant lung cancer." (PMID 27270313, 2016). "In conclusion, this study firstly provides the experience of an in-house molecular diagnostics system in cancer pharmacogenomics, especially EGFR mutations in lung cancer, from setup to routine practice and quality control in Taiwan." (PMID 27480787, 2016). "This categorization is based on the fairly salient fact that most clinically relevant EGFR mutations in lung cancer patients are either deletions in exon 19 or missense mutations in exon 2113." (PMID 26739511, 2016). "One of the most commonly used targeted therapeutic agents for EGFR mutated lung cancers is erlotinib (Tarceva)." (PMID 27092293, 2016). "Under this model, gefitinib or erotinib can kill most of the lung cancer cells harboring EGFR mutations, but the remaining cells are forced into G0 phase and escape from TKI damage." (PMID 27825114, 2016). "The success of EGFR target therapy in lung cancer patients with EGFR mutations initiated the era of molecular diagnostics in cancer management." (PMID 27480787, 2016). "Detection of an epidermal growth factor receptor (EGFR) mutation in circulating cell-free DNA (cfDNA) is a noninvasive method to collect genetic information to guide treatment of lung cancer with tyrosine-kinase inhibitors (TKIs)." (PMID 27081078, 2016). "Increased expression of HER2 was observed in both EGFR exon 21 L858R missense and exon 19 E746-A750 deletion mutations lung cancer stable cells." (PMID 27362942, 2016). "The study showed that approximately half of lung cancer patients with acquired resistance to afatinib had a second EGFR T790M mutation." (PMID 26862733, 2016). "Epidermal growth factor receptor (EGFR) mutation is the most common genetic alteration in East Asians with lung cancer." (PMID 27449093, 2016). "The discovery of activating mutations located in the tyrosine kinase domains of EGFR has expanded the therapeutic options of lung cancer patients since they can be treated by EGFR-TKIs." (PMID 26968814, 2016). "These tumors are found more frequently in women and tend to harbor EGFR mutation compared with other types of lung cancer." (PMID 27526096, 2016). "Effective alternatives are desperately needed in clinic for treating EGFR kinase domain mutation positive lung cancer." (PMID 26654941, 2016). "The most studied missense mutation in this tumor type is in fact EGFR A289V/D/T, known for being resistant to anti-EGFR inhibitor used in lung cancer." (PMID 26860319, 2016). "This is confirmed on another pair of lung cancer cell lines: EGFR mutation positive H1650 cell and EGFR wildtype NCI-H226 cell." (PMID 26654941, 2016). "The results explored that family history of lung cancer is an independent predictor for higher EGFR mutation rate in 1713 lung adenocarcinoma patients (Odd ratio 1.68, 95% CI 1.06–2.67, P = 0.028)." (PMID 27449093, 2016).